NHERF1 (NHERF family PDZ scaffold protein 1)
Diseases named in the same sentence as NHERF1 in open-access papers (continued):
Sharing a sentence is not in itself a finding about the gene and the disease.
breast carcinoma (continued). "Loss of heterozygosity at the NHERF1 gene locus (17q25.1) or somatic intragenic missense mutations occur in the majority of human ovarian and breast cancers but not other diseases examined to date." (PMID 29551770, 2018). "High levels of NHERF1 in breast cancer cells suggest its important roles in breast cancer." (PMID 27448983, 2016). "Our identification here of p-ezrin as a crucial molecule in breast cancer dissemination suggests that the roles of NHERF1 and NHE1 in directing metastasis may well be governed by p-ezrin." (PMID 24086451, 2013). "Furthermore, in the whole series of breast cancers we found cytoplasmic NHERF1 expression positively correlated to VEGFR1 (r = 0.382, p = 0.000), and in VEGFR1-overexpressing tumors the oncogenic receptor co-localized with NHERF1 at cytoplasmic level." (PMID 22439624, 2012). "Our earlier results of NHERF1genetic alterations in human breast cancer prompted us to hypothesize that NHERF1 acts as a tumor suppressor gene in mammary gland." (PMID 18190691, 2008). "It was found that NHERF1 LOH-positive breast cancer cells had reduced NHERF1 expression." (PMID 18190691, 2008). "To explore whether LOH is responsible for a decrease in NHERF1 expression, we correlated the two parameters in 22 breast cancer cell lines that had been tested." (PMID 18190691, 2008). "Our finding of a higher sensitivity of breast cells to STI-571 in the presence of NHERF1 suggests that future investigations of this important pathway may yield new measures to improve breast cancer treatment." (PMID 18190691, 2008). "In agreement with observations of primary breast carcinoma, our panel of breast cancer cell lines revealed an inconsistent relationship between NHERF1 and ER-α positivity, suggesting that regulation of NHERF1 expression exists at levels other than oestrogen stimulation." (PMID 17078868, 2006). "To clarify these contrasting views, we sought to determine whether the proliferation of breast cancer cells is affected by knockdown of NHERF1 expression." (PMID 17078868, 2006). "One way to determine whether NHERF1 functions as a tumour suppressor gene in human breast cancer is to assess the resultant phenotypic responses by knocking down endogenous NHERF1 expression in NHERF1-high expressors." (PMID 17078868, 2006). "To confirm the NHERF1 tumour suppressor activity suggested by our genetic analyses, we used retrovirus-transduced short hairpin RNA (shRNA) to knock down NHERF1 expression in breast cancer cell lines MCF7 and T47D." (PMID 17078868, 2006). "The promoter of NHERF1 gene contains estrogen-responsive elements, and NHERF1 expression was correlated with increasing ER (estrogen receptor) levels in >90% of ER-positive breast carcinomas, while it is absent in ER-negative tumors associated with early recurrence and poor survival." (PMID 29551770, 2018). "Furthermore, aberrant nuclear NHERF1 expression might be important for the carcinogenesis and progression of colon and breast cancer." (PMID 30463370, 2018). "However, whether NHERF1 acts as a tumor suppressor or oncoprotein in breast cancer still remains elusive." (PMID 27448983, 2016). "In addition, the subcellular distribution of NHERF1 could affect the interaction between NHERF1 and downstream signaling proteins, which could impact the oncogenic role of NHERF1 in breast cancer." (PMID 27097111, 2016). "We had already demonstrated a significant change in the pattern of cellular NHERF1 distribution from normal to in situ to invasive BC tissue, showing that cNHERF1 staining accumulation could suggest an important role in breast carcinoma development and tumor progression." (PMID 26312763, 2015). "Furthermore, Nherf1 was reported to localize to pseudopodial tips along with NHE1 and stimulate NHE1 activity, leading to increased invasiveness of breast cancer cells, and loss of Nherf1 enhances Wnt/β-catenin signaling, which is associated with hyperproliferation in breast cancer." (PMID 23593172, 2013).
breast carcinoma (continued). "In addition, interaction of ezrin with other signalling molecules such as the Na+/H+ exchanger regulatory factor (NHERF-1), recently described to be altered in breast cancer, may also be involved." (PMID 15987432, 2005). "Together, these findings suggest that the expression of HER2 combined with the loss of cell polarity facilitate physical interactions between Erbin, NHERF1, Ezrin and HER2 in breast cancer cells." (PMID 40390040, 2025). "In summary, in breast cancer cells, Erbin interacts with HER2 as well as other scaffolding proteins, including NHERF1 and Ezrin." (PMID 40390040, 2025). "NHERF1 suppressed EGFR phosphorylation and inhibited EGF-induced proliferation/migration in breast cancer cells." (PMID 32164629, 2020). "It has been reported that NHERF1 overexpression reduced activation of AKT and ERK signaling as well as proliferative, migratory, and invasive abilities of both breast cancer cells and lung cancer cells." (PMID 28085111, 2017). "Our data identify NHERF1 as a new binding partner for GPER and provide a novel mechanism by which GPER protein level is regulated in breast cancer cells." (PMID 27448983, 2016). "In this study, we identified PDZ protein NHERF1 as a novel GPER-binding partner in both HEK-293 and breast cancer cells by using GST pull-down, co-IP and confocal immunofluorescent assays." (PMID 27448983, 2016). "NHERF1 mRNA levels vary among different human tissues, and NHERF1 is upregulated in several human s, including hepatocellular carcinoma (HCC), breast cancer, and colorectal cancer." (PMID 27097111, 2016). "That NHERF1 elicits suppressor function through PTEN is also indicated by an inverse correlation between intact NHERF1 gene and wild-type PTEN or PI3KCA in breast cancer cells." (PMID 18190691, 2008). "Na+/H+ exchanger regulatory factor 1 (NHERF1, also known as EBP50 or NHERF) is a putative tumour suppressor gene in human breast cancer." (PMID 17078868, 2006). "By the time we observe lumen filling lesions, or in HER2-overexpressing breast cancer cells, basolateral polarization is lost and HER2, Ezrin, NHERF1, HSP90, and Erbin all join together to form stable signaling complexes that localize within protruding membrane domains." (PMID 40390040, 2025). "Erbin co-localized with HER2, NHERF1, and Ezrin at the plasma membrane and especially within membrane protrusions, which we have previously documented to be an important location of active HER2 signaling in breast cancer cells." (PMID 40390040, 2025). "Interestingly, a previous study showed that NHERF1 with a mutation in the PDZ2 domain changes its localization in breast cancer; since we have not observed a similar phenotype with NHERF2, this indicates that modifications in NHERF2 might have exclusive roles in carcinogenesis." (PMID 37623973, 2023). "In summary, NHERF1 expression could be considered a new potential biomarker in combination with PARP1 and BRCA1 expression to stratify breast cancer patients." (PMID 29029467, 2017). "We and other groups reported that NHERF1 could form signaling complexes with PTEN or tyrosine kinase receptors including PDGFR and EGFR to counterbalance AKT and ERK signaling in breast cancer cells." (PMID 28085111, 2017). "Because of the strong correlation between NHERF1 LOH and the aggressive features of breast cancer, we hypothesized that NHERF1 tumor suppressor activity was haploinsufficient." (PMID 18190691, 2008). "Our data indicate that the interaction of NHERF1 with PTEN counterbalances PI3K/Akt oncogenic signaling and may affect how cells respond to PDGFR inhibition in breast cancer." (PMID 18190691, 2008). "It should be pointed out that NHERF1 expression in breast cancer cells is not necessarily correlated with ER-α status." (PMID 17078868, 2006). "In this study, we evaluated NHERF1, BRCA1 and PARP1 protein expression by means of immuno-histochemistry in a retrospective series of invasive BC including a subgroup of triple negative breast cancers (TNBCs)." (PMID 29029467, 2017).
breast carcinoma (continued). "In our previous studies, it was established that NHERF1, an adaptor protein with two non-identical, type 1 tandem PDZ domains and a carboxyl-terminal ezrin-binding domain, is a potential candidate of clinical relevance for human breast cancer." (PMID 23991686, 2013).
cervical carcinoma (16 papers, 2011 to 2024). A carcinoma arising from either the exocervical squamous epithelium or the endocervical glandular epithelium. "The present study showed that NHERF1 was a novel gene associated with both cell proliferation and Wnt signaling pathway in cervical cancer by analysis of differential gene expression and gene cluster for the cervical cancer specimens from GEO data sets." (PMID 29867145, 2018). "Analysis based on a cervical cancer dataset from The Cancer Genome Atlas (TCGA) showed association of NHERF1 expression with disease-free survival of patients received cisplatin treatment." (PMID 28085111, 2017). "Moreover, in vitro data link loss of NHERF-1 in cervical cancer with increase in cellular growth, proliferation, cell cycle, and ERK signaling stimulated by EGFR." (PMID 32695664, 2020). "Wnt signaling and cell proliferation associated with downregulation of NHERF1 might contribute to cervical cancer development and progression." (PMID 29867145, 2018). "Low levels of NHERF1 in cervical cancer specimens were found to associate with activation of cell proliferation and Wnt/β-catenin signaling by gene set enrichment analysis, and also were an independent predictive factor for worse prognosis of cervical cancer patients by Cox regression analysis." (PMID 29867145, 2018). "Further analysis revealed that lower levels of NHERF1 were prominently correlated with activation of Wnt/β-catenin signaling and cell proliferation, and were an independent risk factor for worse prognosis of cervical cancer patients." (PMID 29867145, 2018). "NHERF1 is tumour-suppressive and regulates cellular processes of differentiation and inhibits cervical cancer cell proliferation, thus HPV degrades NHERF1 to delay differentiation and augment proliferation." (PMID 39542216, 2024). "Such protein degradation, caused by the presence of HPV16 E6, has also been observed for NHERF1 in cell lines derived from cervical carcinomas, and in HPV16+ cervical lesions." (PMID 37623973, 2023). "In the last decade, NHERF1 acquired a key role as a prognostic biomarker in cervical cancer (CC) progression." (PMID 35223518, 2022). "The bioinformatics analysis of two GEO datasets and the analysis of validation performed in 31 tissue specimens, demonstrated a down-regulation of NHERF1 expression in cervical cancer samples compared to adjacent normal tissues." (PMID 35223518, 2022). "It is likely that NHERF1 inhibits cervical cancer cell proliferation through the downregulation of the actin cross-linking protein α-Actinin-4 (ACTN4)." (PMID 35223518, 2022). "Recent studies have reported that Na+/H+ exchanger regulatory factor 1 (NHERF1) is associated with cell proliferation through the Wnt/β-catenin signaling and negatively regulates ACTN4 expression in cervical cancer." (PMID 33363146, 2020). "In cervical cancer cells, NHERF1, as a putative interaction partner, reduced the stability of MRP4 by facilitating its internalization from cell surface to sensitize cisplatin-refractory." (PMID 32164629, 2020). "In accordance with this finding, NHERF1 knockdown augmented the ACTN4 protein level in cervical cancer cells." (PMID 31766144, 2019). "Taken together, these data suggest that NHERF1 inhibits cervical cancer cells proliferation through reduction of β-catenin levels by regulation of ACTN4 expression." (PMID 29867145, 2018). "In the present study, we further revealed that NHERF1 inhibition of cervical cancer cell proliferation was mediated via ACTN4." (PMID 29867145, 2018). "Taken together, these data indicate that NHERF1 inhibits cervical cancer cell proliferation via suppression of ACTN4 expression." (PMID 29867145, 2018). "Suppression of NHERF1 in cervical cancer xenograft tumor increased its ACTN4 and β-catenin protein levels, and enhanced the levels of Ki67 by immunohistochemical staining." (PMID 29867145, 2018).
cervical carcinoma (continued). "NHERF1 was further demonstrated to retard cell proliferation with the attenuation of Wnt/β-catenin pathway activation of cervical cancer cells in vivo and in vitro through suppression of α-actinin-4 (ACTN4) expression level." (PMID 29867145, 2018). "It was further demonstrated in cellular study that NHERF1 inhibition of cervical cancer cell proliferation through Wnt/β-catenin signaling was dependent on α-actinin-4 (ACTN4) expression." (PMID 29867145, 2018). "The mRNA levels of NHERF1 of 14 cervical cancer cell lines were analyzed in GSE9750 or GSE89657 data set." (PMID 29867145, 2018). "In summary, the present study provides novel evidences for a tumor-suppressive role of NHERF1 in cervical cancer cell proliferation by attenuation of Wnt/β-catenin signaling via a decrease in ACTN4 expression." (PMID 29867145, 2018). "Our data further showed that the mRNA levels of NHERF1 in HPV-inactive cervical cancer patients were significantly lower and activation of Wnt/β-catenin signaling and proliferation genes were more prominent in this subgroup of patients." (PMID 29867145, 2018). "Taken together, we proposed a possible molecular mechanism for cisplatin resistance in cervical cancer by which downregulation of NHERF1 promotes overactivation of Wnt/β-catenin signaling and results in cisplatin resistance." (PMID 29867145, 2018). "Taken together, these findings indicate that NHERF1 inhibits proliferation of cervical cancer cells." (PMID 29867145, 2018). "In this study, we showed that both gene signatures of cisplatin resistance and Wnt signaling were enriched in NHERF1 low-expression cervical cancer patients." (PMID 29867145, 2018). "The cervical cancer patients were stratified by the lower quartile of NHERF1 level in the specimens as high- and low-expression groups." (PMID 29867145, 2018). "Blocking Wnt/β-catenin signaling abolished the enhancement of cervical cancer cell proliferation induced by knockdown of NHERF1." (PMID 29867145, 2018). "In the present study, we found that NHERF1 inhibited cervical cancer cell proliferation from in vitro and in vivo models, suggesting an anti-proliferation and tumor-suppressive effect of NHERF1 in cervical cancer." (PMID 29867145, 2018). "Downregulation of NHERF1 was verified to be correlated with activation of proliferation, and Wnt/β-catenin signaling and adverse prognosis in cervical cancer." (PMID 29867145, 2018). "In the present study, NHERF1 was a novel downregulated gene involved in Wnt signaling and cell proliferation in cervical cancer." (PMID 29867145, 2018). "In the present study, significant worse prognosis was found in cervical cancer patients with lower levels of NHERF1." (PMID 29867145, 2018). "Taken together, our results provide the first evidence that NHERF1 can sensitize cisplatin-refractory cervical cancer cells." (PMID 28085111, 2017). "Taken together, these data suggest that NHERF1 is involved in the regulation of cisplatin resistance in cervical cancer cells." (PMID 28085111, 2017). "We further characterized the regulatory effect of NHERF1 on response of cervical cancer cells to cisplatin and provided a novel clue for the mechanisms underlying cisplatin resistance." (PMID 28085111, 2017). "In the present study, we found that NHERF1 was downregulated in cisplatin-resistant HeLa cells by analysis of a cervical cancer dataset from Gene Expression Omnibus (GEO)." (PMID 28085111, 2017). "Meanwhile, we found an inverse correlation between expression levels of NHERF1 and MRP4 through analysis of TCGA cervical cancer dataset, suggesting an inhibitory effect of NHERF1 on MRP4 expression." (PMID 28085111, 2017). "In conclusion, our study provides the first evidence that NHERF1 can regulate sensitivity of cervical cancer cells to cisplatin, which offers more insights into the molecular mechanism underlying cisplatin resistance." (PMID 28085111, 2017).